ADTRP (androgen dependent TFPI regulating protein)
Description:
Hydrolyzes bioactive fatty-acid esters of hydroxy-fatty acids (FAHFAs), but not other major classes of lipids. Show a preference for FAHFAs with branching distal from the carboxylate head group of the lipids. Regulates the expression and the cell-associated anticoagulant activity of the inhibitor TFPI in endothelial cells (in vitro).
Synonyms: C6orf105; dJ413H6.1; AIG1L
Tractability: Antibody: UniProt places it where antibodies can reach, with high confidence; UniProt predicts a signal peptide or a membrane-spanning region; its Gene Ontology location is reachable by antibodies, with medium confidence.
Gene: Protein-coding gene on chromosome 6 (11,712,054 to 11,807,046, reverse strand). Ensembl gene ENSG00000111863.
Subcellular location: Cell membrane
Subcellular location (Human Protein Atlas): Nucleoli
Gene Ontology:
Molecular function: protein binding; hydrolase activity
Biological process: cell migration involved in sprouting angiogenesis; cellular response to oxidised low-density lipoprotein particle stimulus; cellular response to steroid hormone stimulus; long-chain fatty acid catabolic process; negative regulation of blood coagulation; negative regulation of extracellular matrix constituent secretion; negative regulation of leukocyte cell-cell adhesion; negative regulation of leukocyte migration; negative regulation of lymphocyte migration; negative regulation of protein secretion; positive regulation of gene expression; positive regulation of phosphatidylinositol 3-kinase/protein kinase B signal transduction
Cellular component: caveola; cell surface; membrane; plasma membrane
Genetic constraint (gnomAD): Loss-of-function variants: 19 observed, 25.97 expected, observed/expected ratio (o/e) 0.73, 90% interval 0.51 to 1.07. The upper end of that interval is the gene's LOEUF score, 1.07, which puts it in group 4 of 6, group 1 being the genes least tolerant of losing a copy. Missense variants: 237 observed, 275.6 expected, observed/expected ratio (o/e) 0.86, 90% interval 0.77 to 0.96. Synonymous variants: 98 observed, 106.61 expected, observed/expected ratio (o/e) 0.92, 90% interval 0.78 to 1.09.
Homologues: Orthologues: chimpanzee ADTRP (99% identical), macaque ADTRP (93% identical), dog ADTRP (75% identical), pig ADTRP (73% identical), rat Adtrp (68% identical), mouse Adtrp (66% identical), guinea pig ADTRP (63% identical), rabbit ADTRP (59% identical), tropical clawed frog adtrp (43% identical), Drosophila melanogaster CG3625 (33% identical), Drosophila melanogaster CG6149 (31% identical), zebrafish adtrp (30% identical), and 5 more. Paralogues in human: AIG1 (34% identical).
Diseases named in the same sentence as ADTRP in open-access papers:
ADTRP is named in the same sentence as 13 diseases in open-access papers, as found by Europe PMC text mining. Sharing a sentence is not in itself a finding about the gene and the disease. The quoted sentences say what the papers report.
atherosclerosis (3 papers, 2015 to 2025). A disease characterized by the build-up of fatty material and calcium deposition in the arterial wall resulting in partial or complete occlusion of the arterial lumen. "It is suggested that a decreased expression of ADTRP may lead to a reduction in TFPI expression and thus result in an increased risk for atherosclerosis and CAD." (PMID 28074087, 2017). "Moreover, ADTRP was recently found to be up-regulated by Peroxisome Proliferator-Activated Receptor γ in human macrophages and atherosclerosis lesions." (PMID 26375920, 2015).
craniosynostosis (1 paper, 2021). Craniosynostosis is defined as the premature fusion of one or more cranial sutures leading to secondary distortion of skull shape resulting in skull deformities with a variable presentation. "Deficiency of ADTRP in oral cleft syndrome and craniosynostosis suggests that ADTRP may play significant roles in the epithelial to mesenchymal transition during palatogenesis, and MSC differentiation into chondrocytes and osteocytes." (PMID 33923232, 2021).
Graves disease (1 paper, 2025). Graves' disease is an autoimmune disorder that leads to overactivity of the thyroid gland (hyperthyroidism).It is caused by an abnormal immune system response that causes the thyroid gland to produce too much thyroid hormones. "XIST, PPP1R2C, CALHM6, AL672277.1, TSIX, SHROOM1, ADTRP, JUND, SGK1, CHKA, AO008569.1, MAP7D2, and AIF1 were down-expressed genes in TS compared with both the healthy female and the female patient with Graves’ disease." (PMID 39851522, 2025).
hyperlipidemia (1 paper, 2014). "ADTRP (rs6903956), CDKN2A/B (rs10757274) and clinical characteristics (T2DM, hypertension and hyperlipidemia) were included in the gene-environment interactions analysis, adjusting for age, gender, ethnicity, BMI, and smoking and drinking habits as covariates." (PMID 25430018, 2014).
Obesity (1 paper, 2017). Accumulation of substantial excess body fat. "The mechanistic relationships between obesity, androgens, ADTRP, TF and TFPI have not been studied in relation to uterine fibroids, and the relationships we detect here require additional functional studies." (PMID 28715450, 2017).
cancer (1 paper, 2021). A tumor composed of atypical neoplastic, often pleomorphic cells that invade other tissues. "Previous studies on AIGs demonstrated that one member of the gene family, AIG1, is involved in many biological processes in cancer cell lines and that ADTRP is associated with cardiovascular diseases." (PMID 34440364, 2021).
cardiovascular diseases (1 paper, 2021). "In contrast to that of its paralog, the validation of ADTRP was provoked by its potential roles in cardiovascular diseases." (PMID 34440364, 2021).
metabolic disorders (1 paper, 2015). "These information together suggest that ADTRP may be involved in insulin-mediated metabolism regulation and metabolic disorders, such as CAD." (PMID 26375920, 2015).
ADTRP also shares sentences with these, for which no sentence is quoted: coronary heart disease (1 paper); dyslipidemia (1); fibroid (1); Hypertension (1); Turner syndrome (1).